MOCOS (molybdenum cofactor sulfurase)
Description:
Sulfurates the molybdenum cofactor. Sulfation of molybdenum is essential for xanthine dehydrogenase (XDH) and aldehyde oxidase (ADO) enzymes in which molybdenum cofactor is liganded by 1 oxygen and 1 sulfur atom in active form. In vitro, the C-terminal domain is able to reduce N-hydroxylated prodrugs, such as benzamidoxime.
Synonyms: MCS; MOS; hMCS; FLJ20733
Tractability: PROTAC: ubiquitination databases record sites on it.
Gene: Protein-coding gene on chromosome 18 (36,186,894 to 36,272,157, forward strand). Ensembl gene ENSG00000075643.
Subcellular location (Human Protein Atlas): Mitochondria; Cytosol
Pathways (Reactome):
Metabolism: Molybdenum cofactor biosynthesis
Gene Ontology:
Molecular function: molybdenum cofactor sulfurtransferase activity; protein binding; catalytic activity; lyase activity; molybdenum ion binding; pyridoxal phosphate binding
Biological process: Mo-molybdopterin cofactor biosynthetic process; molybdopterin cofactor biosynthetic process; molybdopterin cofactor metabolic process
Cellular component: cytosol
Genetic constraint (gnomAD): Loss-of-function variants: 86 observed, 86.47 expected, observed/expected ratio (o/e) 0.99, 90% interval 0.83 to 1.19. The upper end of that interval is the gene's LOEUF score, 1.19, which puts it in group 5 of 6, group 1 being the genes least tolerant of losing a copy. Missense variants: 1,120 observed, 1,153.2 expected, observed/expected ratio (o/e) 0.97, 90% interval 0.92 to 1.02. Synonymous variants: 445 observed, 440.01 expected, observed/expected ratio (o/e) 1.01, 90% interval 0.94 to 1.09.
Gene-disease validity (ClinGen):
ClinGen rates the evidence that MOCOS causes each of these diseases.
xanthinuria type II (autosomal recessive): Definitive.
Homologues: Orthologues: chimpanzee MOCOS (99% identical), macaque MOCOS (95% identical), dog MOCOS (80% identical), guinea pig MOCOS (78% identical), rabbit MOCOS (75% identical), pig MOCOS (75% identical), mouse Mocos (74% identical), rat Mocos (69% identical), tropical clawed frog MOCOS (53% identical), Drosophila melanogaster mal (34% identical), Caenorhabditis elegans mocs-1 (29% identical). Paralogues in human: MTARC2 (10% identical), MTARC1 (10% identical).
Diseases named in the same sentence as MOCOS in open-access papers:
MOCOS is named in the same sentence as 18 diseases in open-access papers, as found by Europe PMC text mining. Sharing a sentence is not in itself a finding about the gene and the disease. The quoted sentences say what the papers report.
xanthinuria (11 papers, 2012 to 2025). A metabolic metabolic disorder characterized by excess urinary excretion of the purine base xanthine. "Pathogenic variants in MOCOS have previously been associated with inherited metabolic syndromes and xanthinuria in different species including Japanese Black cattle." (PMID 27919260, 2016). "Xanthinuria Type II and Xanthinuria are diseases associated with the MOCOS gene." (PMID 34941638, 2021). "Genetic causes of xanthinuria with NL and/or NC consist of Xanthinuria (XDH and MOCOS genes) and Molybdenum cofactor deficiency (MOCS1 and MOCS2 genes)." (PMID 38606357, 2024). "For instance, we detected frameshift and missense variants in MOCOS and SLC45A2 that are associated with recessive xanthinuria and oculocutaneous albinism, respectively." (PMID 31914939, 2020). "Type I xanthinuria involves XOR deficiency due to genetic defect of XOR, whereas type II xanthinuria involves dual deficiency of XOR and aldehyde oxidase (AO, a molybdoflavo enzyme similar to XOR) due to genetic defect in the molybdenum cofactor sulfurase." (PMID 23203137, 2012). "Classically, Type I xanthinuria is caused by a mutation in XDH/XO gene mapped to chromosome 2p23.1, whereas Type II xanthinuria is caused by deficits of XDH/OX and aldehyde oxidase (AO) caused by mutations in molybdenum cofactor sulfurase gene (MOCOS) localized on chromosome 18q12.2." (PMID 30157195, 2018). "Disorders of uric acid metabolism had 12 genetic results on xanthinuria (XDH and MOCOS) and renal hyperuricemia (SLC22A12) genes, affecting 11 patients (10%)." (PMID 40126616, 2025).
xanthinuria type II (7 papers, 2020 to 2025). "In patients diagnosed with xanthinuria type II caused by MOCOS gene variants, the use of purine drugs should be prohibited to avoid serious adverse events." (PMID 41164817, 2025). "The downregulation and diminished activity of MOCOS were recently associated with autism and other neuropsychiatric disorders, and at least one case of type II xanthinuria associated with autism was reported." (PMID 34356852, 2021). "We reported six novel pathogenic variants, and for the first time, we characterized MOCOS variants underlying type II xanthinuria by in vitro expression studies." (PMID 34356852, 2021). "Classical xanthinuria is a rare autosomal recessive metabolic disorder caused by variants in the XDH (type I) or MOCOS (type II) genes." (PMID 34356852, 2021). "Additionally, we have summarized the clinical characteristics and genetic variants of previously reported cases of MOCOS defect-associated Xanthinuria type II to enhance the understanding of the diagnosis and treatment of hypouricemia." (PMID 41164817, 2025). "Notably, Xanthinuria type II caused by pathogenic or likely pathogenic variants of the MOCOS gene is a very rare disease, and most of the previous reports were case studies, with no cohort studies." (PMID 41164817, 2025). "Notably, although the serum and urine levels of xanthine and hypoxanthine as well as the activity of XDH, AOX1, and MOCOS are important diagnostic criteria for Xanthinuria type II, these tests cannot be performed in most hospital laboratories." (PMID 41164817, 2025). "When type II xanthinuria was diagnosed by an allopurinol loading test in family F3, we assumed that these families may share a common variant in the MOCOS gene." (PMID 34356852, 2021). "Given the severe defects in the MOCOS gene-deficient mouse model, additional research is needed to clarify the clinical profile of Xanthinuria type II and the other roles of MOCOS in metabolic pathways." (PMID 41164817, 2025). "Further research is required to elucidate the clinical profile of Xanthinuria type II and identify the other roles of MOCOS in metabolic pathways." (PMID 41164817, 2025). "In type II xanthinuria, (MIM 603592) variants in the Molybdenum Cofactor Sulfurase gene (MOCOS, alias HMCS) cause combined XDH and Aldehyde Oxidase (AO; EC 1.17.3.2) deficiency." (PMID 34356852, 2021). "Additionally, mutations in the molybdenum cofactor sulfurase gene (MOCOS, EC: 2.8), mapped to chromosome 18q12.2, raise xanthinuria type II (OMIM 603592), developing both XDH/XO and aldehyde oxidase (AOX) deficiency." (PMID 37360896, 2021). "However, even though several variants have been reported to be linked with type II xanthinuria, no direct correlation has been provided so far between the variant and the precise biochemical effects on MOCOS enzymes." (PMID 34356852, 2021).
clear cell renal cell carcinoma (1 paper, 2020). "In clear cell renal cell carcinoma (ccRCC), CLIP4 mutations are three-fold higher in patients with aggressive tumors than in those without aggressive ccRCC, and high expression levels of MOCOS, BAIAP2L1, DDX11, and CLIP4 are markedly associated with poor OS." (PMID 33575272, 2020).
Insulin resistance (1 paper, 2019). Increased resistance towards insulin, that is, diminished effectiveness of insulin in reducing blood glucose levels. "Vitamin K epoxide reductase complex, subunit 1-like 1 (VKORC1L1), BTD, GPC1, MOCOS, GPC5, AKR1C4, and NMNAT2 are novel biomarkers for the development of insulin resistance." (PMID 30678306, 2019).
lung carcinoma (1 paper, 2020).
nephrolithiasis (1 paper, 2025). The presence of a calculus in the pelvis of the kidney; this is most often composed of mineral salts and proteins. "Nephrolithiasis or urinary tract stones (formed due to xanthine accumulation) have been described in eight cases with MOCOS gene defects." (PMID 41164817, 2025).
MOCOS also shares sentences with these, for which no sentence is quoted: amyotrophic lateral sclerosis (1 paper); Asperger syndrome (1); autism (1); cancer (1); infection (1); metabolic disorder (1); metabolic syndrome (1); neurodegenerative disease (1); neurodevelopmental disorder (1); oculocutaneous albinism (1); Parkinson disease (1); xanthinuria type I (1).